POLA2 (DNA polymerase alpha 2, accessory subunit)
Description:
Accessory subunit of the DNA polymerase alpha complex (also known as the alpha DNA polymerase-primase complex) which plays an essential role in the initiation of DNA synthesis. During the S phase of the cell cycle, the DNA polymerase alpha complex (composed of a catalytic subunit POLA1, an accessory subunit POLA2 and two primase subunits, the catalytic subunit PRIM1 and the regulatory subunit PRIM2) is recruited to DNA at the replicative forks via direct interactions with MCM10 and WDHD1 (By similarity). The primase subunit of the polymerase alpha complex initiates DNA synthesis by oligomerising short RNA primers on both leading and lagging strands (By similarity). These primers are initially extended by the polymerase alpha catalytic subunit and subsequently transferred to polymerase delta and polymerase epsilon for processive synthesis on the lagging and leading strand, respectively (By similarity).
Synonyms: FLJ21662
Tractability: Small molecule: an approved drug acts on it; a structure with a bound ligand is known. PROTAC: ubiquitination databases record sites on it; its protein half-life has been measured.
Gene: Protein-coding gene on chromosome 11 (65,261,913 to 65,305,959, forward strand). Ensembl gene ENSG00000014138.
Subcellular location: Nucleus
Subcellular location (Human Protein Atlas): Nucleoplasm; Basal body; Cytosol
Pathways (Reactome):
DNA Replication: Activation of the pre-replicative complex; DNA replication initiation; Polymerase switching; Processive synthesis on the lagging strand; Removal of the Flap Intermediate
Cell Cycle: Inhibition of replication initiation of damaged DNA by RB1/E2F1; Polymerase switching on the C-strand of the telomere; Telomere C-strand synthesis initiation
Disease: Defective pyroptosis
Gene Ontology:
Molecular function: protein binding; DNA binding
Biological process: DNA replication initiation; DNA replication, synthesis of primer; DNA replication
Cellular component: alpha DNA polymerase:primase complex; nucleoplasm; nucleus
Genetic constraint (gnomAD): Loss-of-function variants: 27 observed, 53.23 expected, observed/expected ratio (o/e) 0.51, 90% interval 0.37 to 0.7. The upper end of that interval is the gene's LOEUF score, 0.7, which puts it in group 2 of 6, group 1 being the genes least tolerant of losing a copy. Missense variants: 466 observed, 569.83 expected, observed/expected ratio (o/e) 0.82, 90% interval 0.76 to 0.88. Synonymous variants: 220 observed, 235.93 expected, observed/expected ratio (o/e) 0.93, 90% interval 0.83 to 1.04.
Homologues: Orthologues: chimpanzee POLA2 (99% identical), macaque POLA2 (98% identical), rabbit POLA2 (89% identical), dog POLA2 (88% identical), guinea pig POLA2 (86% identical), pig POLA2 (85% identical), rat Pola2 (84% identical), mouse Pola2 (83% identical), tropical clawed frog pola2 (65% identical), zebrafish pola2 (56% identical), Drosophila melanogaster PolA2 (30% identical), Caenorhabditis elegans div-1 (25% identical).
Diseases named in the same sentence as POLA2 in open-access papers:
POLA2 is named in the same sentence as 36 diseases in open-access papers, as found by Europe PMC text mining. Sharing a sentence is not in itself a finding about the gene and the disease. The quoted sentences say what the papers report.
lung carcinoma (7 papers, 2016 to 2025). "Here, we determined the association between POLA2 and gemcitabine treatment in human lung cancer cells." (PMID 28155658, 2016). "In the current study, we sought to determine the association between POLA2 and gemcitabine treatment, and further characterized the role of POLA2 in human lung cancer cells." (PMID 28155658, 2016). "In this current study, we reported that the response to gemcitabine treatment is related to POLA2 and confirmed that the knockdown of POLA2 gene increased the resistance to gemcitabine treatment in human lung cancer cells." (PMID 28155658, 2016). "Collectively, our findings showed that knockdown of POLA2 increases gemcitabine resistance in human lung cancer cells." (PMID 28155658, 2016). "The carcinogenesis of POLA2 has been reported in hepatocellular carcinoma and lung cancer." (PMID 40366506, 2025). "Single nucleotide polymorphisms (SNP) in genes, such as ALDH7A1, POLA2, LIG1, and ERCC6L, are important for the development of various cancers, such as esophageal squamous cell carcinoma, lung cancer, and oral cancer, but these polymorphic genes may be linked with pathogenesis of BRCA." (PMID 31311202, 2019). "Contribution to lung cancer stemness was reported for circ_POLA2 via miR-326/GNB1 axis, where the circ_POLA2 was highly expressed in lung cancer tissues and predicted a poor prognostic outcome." (PMID 38501058, 2024).
ovarian carcinoma (4 papers, 2015 to 2022). A malignant neoplasm originating from the surface ovarian epithelium. "DNA polymerase α2 accessory subunit (POLA2), a subunit of DNA polymerase α regulating DNA replication, was identified as a prognostic biomarker for ovarian cancer and gastric carcinoma." (PMID 32766125, 2020). "Recent studies reported that POLA2 may participate in gene fusion events that can contribute to prognosis in ovarian cancer and gastrointestinal stromal tumors." (PMID 28155658, 2016).
glioblastoma multiforme (3 papers, 2020 to 2025). "POLA2 has been implicated in a wide variety of tumor types (breast cancer, bladder cancer, glioblastoma multiforme, gastrointestinal stromal tumor, non-small cell lung cancer, ovarian cancer) and serves as a prognostic marker for patients." (PMID 40366506, 2025). "Lastly, we observe that POLA2 is elevated in glioblastoma multiforme (GBM) patient samples and this elevated expression correlated with poor overall survival." (PMID 32549188, 2020). "ST1926 similarly reduced TOP2A and POLA2 in glioblastoma cell lines." (PMID 40429796, 2025).
hepatocellular carcinoma (3 papers, 2023 to 2025). A malignant tumor that arises from hepatocytes. "We identified 4 hub genes, namely, LAMA4, POLA2, RAD51, and TYMS, which were used as the final variables, and found that AdaBoostClassifie was the best algorithm for the classification and diagnosis model of hepatocellular carcinoma." (PMID 37051625, 2023).
bladder cancer (2 papers, 2017 to 2025). "Thus, it was very essential to explore the correlations among FGFR3, KIAA1377, POLA2, and EPHA4 in bladder cancer, as well as other cancers or diseases." (PMID 28320388, 2017).
heart failure (2 papers, 2021 to 2024). Inability of the heart to pump blood at an adequate rate to meet tissue metabolic requirements. "One of the hematological traits associated with POLA2 is the mean corpuscular volume, which has been previously related with heart failure." (PMID 34714828, 2021). "We validated a concordant direction of effect sizes of CTBP1, PPM1G, SEPT2, and KRTCAP3 for gout; SKIV2L for heart failure; and AAK1, MAPKAPK5-AS1, POLA2, RSG1, and WWP2 for hypertension." (PMID 38658550, 2024).
adenoma (1 paper, 2024). A neoplasm arising from the epithelium. "Some MP-RNAs interacted with much more partners in adenoma and cancer tissues than in paracancer tissues, such as SLC16A14, POLA2, PCDH11X, TASP1, TSPY20P." (PMID 38773399, 2024).
cervical cancer (1 paper, 2020). A primary or metastatic malignant neoplasm involving the cervix. "Circ_POLA2 regulates cervical cancer cell growth and metastasis via sponging miR-326." (PMID 32766125, 2020). "Cervical cancer cell lines (Hela, SW756, CaSki, C-33a, and SiHa) also had higher levels of circ_POLA2 than that in human cervical epithelial cell line CerEpiC." (PMID 32766125, 2020).
clear renal cell carcinoma (1 paper, 2025). "NUF2 expression positively correlates with tumor-infiltrating CD8+ T cells and dendritic cells in clear renal cell carcinoma, while POLA2 has been identified as a positive biomarker for PD-L1 blockade response in mUC." (PMID 41357226, 2025).
glioma (1 paper, 2020). A benign or malignant brain and spinal cord tumor that arises from glial cells (astrocytes, oligodendrocytes, ependymal cells). "We found that POLA2 expression is elevated in glioma patients and this elevation is associated with poor overall survival." (PMID 32549188, 2020).
telomere syndrome (1 paper, 2021). Accelerated aging syndromes often caused by inheritable gene mutations resulting in decreased telomere lengths. "Two mutations associated with the telomere syndromes Coats Plus and DC, A227V and V259M, were previously shown to halt nuclear localization and diminish PolA1 and PolA2 association with CST14." (PMID 33731801, 2021).
tumor (14 papers, 2014 to 2025). "We then proceeded to silence the POLA2 gene by siRNA transfection and found that instead of causing tumor cell death due to termination of DNA replication, the cell lines became more resistant to gemcitabine treatment." (PMID 28155658, 2016). "Consistent with our prediction, edited POLA2 only influenced the tumor-infiltration of CD8+ T cells and impaired CD8+ T cell cytotoxicity in PCa." (PMID 40366506, 2025). "Correspondingly, heavier tumor weight was measured in ed-Myo19 group in comparison with Blank and wt-POLA2 groups." (PMID 40366506, 2025). "In this study, A-to-I RNA overediting of POLA2 was identified in PCa patients, which was related to tumor stage, tumor recurrence and bad prognosis." (PMID 40366506, 2025). "Just as we predicted, Flow cytometry analysis showed the decreased frequency of CD8+ T cells in mice tumor containing ed-POLA2 compared to mice tumors in Blank and wt-POLA2 groups." (PMID 40366506, 2025). "The 4 risk genes of LAMA4, POLA2, RAD51, and TYMS showed significant differences in the expression of normal and tumor tissues, and the 4 genes showed high expression in tumor tissues." (PMID 37051625, 2023). "To investigate the role of POLA2 in EOCRC tumorigenesis, we first evaluated POLA2 expression in tumor and adjacent normal tissues from multiple databases, including TCGA/GTEx samples, GEO datasets, and our own CRC patients." (PMID 36869385, 2023). "In validation cohort, POLA2 significantly related to tumor differentiation, tumor size and Ki-67 (p < 0.05)." (PMID 37452331, 2023). "This indicates that POLA2 downregulation combined with suppression of apoptosis disrupts epithelial integrity, which can exacerbate cell motility and invasiveness, often considered a prerequisite for tumor infiltration and metastasis." (PMID 40075075, 2025). "Collectively, POLA2 overediting stimulates PCa tumor growth in vivo by upregulating BTBD7." (PMID 40366506, 2025). "We analyzed whether the induction of G2/M transition in the POLA2-i + p35 context could enhance tumor growth." (PMID 40075075, 2025). "Tumor size is larger in ed-POLA2 group compared to wt-POLA2 and Blank groups." (PMID 40366506, 2025). "Meanwhile, PCa patients with tumor recurrence had a higher frequency of POLA2 editing than those without." (PMID 40366506, 2025). "This confers a protective effect in NSCLC patients who possess the POLA2+1747 GG/GA SNP genotype, as the tumour DNA could not replicate." (PMID 25521664, 2014).
cancer (11 papers, 2015 to 2025). A tumor composed of atypical neoplastic, often pleomorphic cells that invade other tissues. "Overexpression of TOP2A and POLA2 has been strongly associated with enhanced cancer cell proliferation, and the observed downregulation of these proteins following ST1926 treatment indicates a potential reduction in cellular proliferation activity." (PMID 40429796, 2025). "Hits that scored as selective dependencies in the dual ARID1 paralog-deficient setting included POLA2, RAPTOR, and NUP50, corresponding to pathways such as MYC targets, G2/M checkpoint, DNA replication and undifferentiated cancer signatures." (PMID 41279405, 2025). "Data from the Oncomine database also suggested that POLA2 amplification frequently occurred across cancer types." (PMID 36869385, 2023). "The A-to-I RNA editing of POLA2 was mediated by ADAR1 enzyme in human cancers." (PMID 40366506, 2025). "More importantly, POLA2 has been found to regulate immune infiltration in human cancers." (PMID 40366506, 2025). "A-to-I RNA editing of POLA2 is mediated by ADAR1 enzyme in cancers." (PMID 40366506, 2025). "The role of A-to-I RNA editing POLA2 has not been investigated in any human cancers and is firstly confirmed in PCa." (PMID 40366506, 2025).
kidney disease (1 paper, 2025). "Further delineation of POLA2-related phenotypes in additional families is needed to understand the potential causative link between POLA2 and kidney disease." (PMID 39616267, 2025).
neurological disorders (1 paper, 2022). "Most importantly, several DEGs such as CX3CL1, SEMA3F, OPHN1, POLA2, MCM10 and POLD3 were found to be associated with neuronal/brain process and genome stability, that is known to be relevant during neurological disorders." (PMID 36267332, 2022).
POLA2 also shares sentences with these, for which no sentence is quoted: esophageal squamous cell carcinoma (2 papers); infection (2); acute myeloid leukemia (1); brain glioma (1); cervical squamous cell carcinoma (1); Coats plus syndrome (1); colorectal cancer (1); DiGeorge syndrome (1); gastric carcinoma (1); gastrointestinal stromal tumor (1); gout (1); HIV-1 infection (1); Hyperglycemia (1); Hypertension (1); liver disease (1); lung adenocarcinoma (1); melanoma (1); mesothelioma (1); non-small cell lung carcinoma (1); oral cancer (1); prostatic cancer (1).